IL22 (interleukin 22)
Diseases named in the same sentence as IL22 in open-access papers (continued):
Sharing a sentence is not in itself a finding about the gene and the disease.
Sjögren’s syndrome (13 papers, 2013 to 2025). "The elevated expression of IL-36α in patients with Sjogren's syndrome is positively associated with the expression of IL-22, IL-17 and IL-23p19 in the lip gland tissues." (PMID 30356900, 2018). "Development of mature FRCs from precursor cells in SLO is driven by LTβR signalling, and TLS-forming FRC-like ‘immunofibroblasts’ have been shown to be regulated by LTα1b2 and IL22 in Sjogren’s syndrome." (PMID 39757146, 2025). "IL-22 is expressed at elevated levels in primary Sjogren’s syndrome patients and plays a proinflammatory role in promoting salivary gland inflammation early in the disease course." (PMID 39630234, 2025). "In labial salivary glands from patients with primary Sjögren’s syndrome, IL-22 has been shown to be produced by activated dendritic cells, T cells, and the NKp44+ subset of NK cells." (PMID 27347394, 2016). "IL-22 levels are elevated in salivary glands of Sjögren’s syndrome (SS) patients, but its role in the pathogenesis of this disease remains unclear." (PMID 36361787, 2022). "Further insights into the possible role of IL-22 have been investigated in a virus-induced mouse model of Sjögren’s syndrome, where IL-22 was found to be mainly produced in the early stages of infection by γδ T cells and then later by αβ T cells, with lesser amounts coming from ILCs and NK cells." (PMID 27347394, 2016). "Although IL-22 may be a potential therapeutic target in primary Sjögren’s syndrome, its role in promoting tissue regeneration and restoring barrier function after tissue injury may preclude systemic IL-22 blockade over long periods of time." (PMID 27347394, 2016). "In addition, CXCL13 production may be mediated by IL-1 in mice infected with IAV, by IL-22 in a mouse model of Sjögren’s syndrome and by TNF-α in the fat." (PMID 37047294, 2023). "Interestingly, IL-22, IL-23 and IL-17 were shown to be significantly increased at both protein and mRNA levels in inflamed salivary glands of patients with primary Sjögren’s syndrome (pSS), indicating that the Th17/IL-23 system may play a pro-inflammatory role in the pathogenesis of pSS." (PMID 35310855, 2022).
depression (12 papers, 2019 to 2025). "This is important because the COX-2/PGE2/IL-22 axis is known to contribute to inflammation-associated neuronal damage and to promote the production of other pro-inflammatory mediators involved in the pathophysiology of depression." (PMID 38218856, 2024). "However, IL-22 was also negatively associated with eating disorder psychopathology, depression and illness duration in the AN sample, indicating that a greater severity of psychiatric illness is linked to lower IL-22." (PMID 34442458, 2021). "Moreover, IL-22 has been linked to several conditions involving inflammatory tissue pathology such as Alzheimer’s disease and multiple sclerosis, and, more recently, depression." (PMID 38791125, 2024). "Initially, concentrations of the anti-inflammatory cytokine IL-22 are markedly diminished in individuals with depression, and the administration of exogenous IL-22 ameliorates stress-induced depressive behaviors." (PMID 40843192, 2025). "This study, through technical means such as cell and animal experiments, for the first time clarified that fluoxetine combined with Longya Lily exerts a therapeutic effect on depression by regulating inflammatory response through the COX-2/PGE2/IL-22 axis." (PMID 38218856, 2024). "Firstly, our study primarily focuses on the role of the COX-2/PGE2/IL-22 axis in neuroinflammatory response in depression, while investigating other possible inflammatory regulatory pathways is not comprehensive enough." (PMID 38218856, 2024). "In doing so, levels of IL-17E and IL-22 are correlated with the co-occurrence of depressive disorders." (PMID 38892934, 2024). "The results of this study represent an essential contribution to this emerging field of research and may be vital in paving the way for novel therapeutic strategies targeting the COX-2/PGE2/IL-22 axis in depression and other neuropsychiatric disorders." (PMID 38218856, 2024). "Therefore, a combination of Longya Lilium with Fluoxetine inactivates the COX-2/PGE2/IL-22 axis, consequently relieving the neuroinflammatory response and the resultant depression." (PMID 38218856, 2024). "In summary, silencing IL-22 could inhibit the inflammatory response and reduce depression-like behaviors in mice." (PMID 38218856, 2024). "Limited studies explore the role of IL-22 in depression through COX-2 inhibition, which may serve as a potential antidepressant treatment." (PMID 38791125, 2024). "Finally, we sought to identify whether Longya Lilium combined with fluoxetine can improve the neuroinflammatory response in mice with depression by inhibiting the COX-2/PGE2/IL-22 axis." (PMID 38218856, 2024). "Therefore, it is speculated that COX-2 may participate in the inflammatory response and contribute to the progression of depression through the PGE2/IL-22 axis, activating microglia in particular." (PMID 38218856, 2024).
enthesitis (12 papers, 2013 to 2025). Inflammation at the site of insertion of ligaments, tendons, and other fibrous structures into bone. "Together these results indicate that the pathophysiology of enthesitis is mediated by IL-23 and its downstream targets, IL-17 and IL-22, whereas IL-22 is specifically involved in the osteoproliferation component of the disease." (PMID 31164157, 2019). "In SKG mice that developed a SpA disease after microbial antigen injection, IL-22 together with IL-17A have been shown to promote peripheral enthesitis." (PMID 30057583, 2018). "Both IL-17 and IL-22 contribute to enthesitis and CCR6 + Th17 cells expand in inflamed joints." (PMID 40938333, 2025). "In addition to IL-17A, IL-22, as a downstream cytokine of IL-23, was shown to be relevant for the severity of enthesitis in both the IL-23mc and SKG mice model." (PMID 34267743, 2021). "However, histological scores focusing on PsA features such as synovial proliferation, enthesitis, bone erosion and joint destruction showed that disease was more severe and destructive in K23/IL-22−/− when compared to K23/IL-22+/+ animals." (PMID 32427877, 2020). "Blocking IL-22 in SKG mice for 8 weeks from the first moment of clinical manifestations reduced Achilles tendon enthesitis, similar to the reduced severity of enthesitis observed in the IL-17A-/- SKG mice." (PMID 34267743, 2021). "The IL-23-mediated enthesitis is reduced in the presence of IL-17 and IL-22 neutralizing antibodies; however, in contrast to IL-22, IL-17 alone is not sufficient to induce enthesitis." (PMID 23984335, 2013). "Importantly, in B10.RIII mice, systemic expression of IL-23 sufficiently induced enthesitis in both the front and back paws without synovial joint destruction and promoted IL-17 and IL-22 expression by these entheseal cells." (PMID 31164157, 2019).
injury (12 papers, 2017 to 2024). Damage inflicted on the body as the direct or indirect result of an external force, with or without disruption of structural continuity. "However, although accumulating evidence indicates IL‐22 is an effective therapeutic antidote for kidney injury, little is known about the underlying mechanisms of IL‐22‐induced TECs recovery." (PMID 33634980, 2021). "In AD-induced acute lung injury, IL-22 inhibits Ang II-mediated pulmonary microvascular endothelial cell apoptosis and downregulates STAT3 expression and intranuclear delivery." (PMID 38971897, 2024). "The authors found that treatment with IL-22-producing L. reuteri upregulated intestinal Reg3γ levels and alleviated alcohol-induced liver injury." (PMID 37908362, 2023). "Interleukin‐22 (IL‐22) is an effective therapeutic antidote for kidney injury via promoting kidney recovery, but little is known about the underlying molecular mechanisms." (PMID 33634980, 2021). "Rationale: Interleukin 22 (IL-22) is an epithelial survival cytokine that is at present being explored as therapeutic agents for acute and chronic liver injury." (PMID 32483425, 2020). "Taken together, these data suggest that miR-29b-2-5p may regulate the balance of Th17/Th22 subsets during acute lung injuries by altering AhR mRNA, which thereby alters the expression of IL-22 and RORc." (PMID 36809070, 2023). "For example, STAT3 activation by IL-6 potentiates proinflammatory responses in peritoneal macrophages, whereas STAT3 activation by IL-10 dampens lipopolysaccharide (LPS)-induced inflammatory responses in Kupffer cells, and STAT3 activation by IL-22 ameliorates ethanol-induced liver injury." (PMID 31931878, 2020). "Furthermore, the other study has shown that enhanced autophagy contributes to the protective effects of IL-22 against acetaminophen-induced liver injury." (PMID 33071774, 2020). "However, serum IL-22 concentrations on PICU admission were significantly lower in patients with SALI compared to septic patients without liver injury (p = 0.021)." (PMID 33177520, 2020).
intestinal inflammation (12 papers, 2014 to 2025). "HO-1 has been shown to play a protective role in DSS-induced intestinal inflammation, with previous research showing that IL-22 can directly stimulate HO-1 in keratinocytes and in the liver." (PMID 40791589, 2025). "This study assesses the influence of tryptophan metabolism, and particularly the microbiota-induced AhR expression, on intestinal homeostasis disturbance following gastroenteritis resolution, and evaluates the efficacy of IL-22 cytokine vectorization on PI-IBS symptoms." (PMID 35090380, 2022). "The protective γδT cells were found to accumulate during DSS or pathogen-induced intestinal inflammation and produce KGF and IL-22, which promotes tissue repair and epithelial cell healing." (PMID 28747917, 2017). "In support of the hypothesis, Zheng and coworkers demonstrated that administration of exogenous mouse or human RegIIIγ, which acts on gram-positive bacteria, to IL-22 deficient mice infected with gram-negative C. rodentium, partly protected these mice from gastroenteritis." (PMID 25799189, 2015).
pancreatitis (12 papers, 2011 to 2025). Inflammation of the pancreas. "In pancreatitis-associated lung injury, IL-22 deficiency exacerbates damage, while exogenous IL-22 reduces apoptosis via Bcl-2 induction." (PMID 40141214, 2025). "Exogenous recombinant IL22 protects mice against acute severe pancreatitis-associated lung injury by regulating the apoptotic balance to strengthen the pulmonary microvascular endothelial barrier via the STAT3 signaling pathway." (PMID 37189778, 2023). "IL-22 plays an important role in inflammatory processes through up-regulation of acute phase reactions and of pancreatitis-associated protein." (PMID 21625390, 2011). "Our data confirm this pattern, while the level of interleukin-6 remained at the same level, and the degree of decrease in IL-22 was associated with the severity of the course – the more pronounced the decrease was observed in patients with the more severe course of pancreatitis." (PMID 39694959, 2024). "IL-22 levels in the blood of patients with pancreatitis correlate with the severity of the disease and the degree of organ dysfunction, making it an important prognostic marker." (PMID 39694959, 2024). "Accumulating evidence indicates that autophagy within acinar cells plays a crucial role in the development of pancreatitis and that IL-22 can inhibit this process." (PMID 38750415, 2024). "IL-22 values were also higher in the group with severe pancreatitis, however, on day 2, its level became lower compared to the group of patients with moderate and mild pancreatitis." (PMID 39694959, 2024). "Liver-specific IL-22 transgenic mice or pre-treatment wild type mice with IL-22 were significantly resistant to cerulein-induced pancreatitis by inhibiting autophagic pathway." (PMID 33177520, 2020). "We and others previously reported that IL-22 treatment protects against cerulean-induced pancreatitis in mice by targeting pancreatic acinar cells." (PMID 26064446, 2015). "This activation in acinar cells contributes to the protective effects exerted by IL-22 on acinar cells and pancreatitis." (PMID 26064446, 2015). "The involvement of IL-22 in pancreatitis is less studied, but emerging evidence suggests it may have a protective role in pancreatic tissue during inflammation." (PMID 39694959, 2024). "Targeting the IL-22–IL-22R1 system might benefit chronic inflammatory diseases concerning the skin, chronic infections, pancreatitis, and so forth, although therapeutic modulation should be individualized." (PMID 27829708, 2016). "On the other hand, pancreatitis might benefit from supplementation of IL-22 because of its protective effects on pancreatic acinar cells and islet cells." (PMID 27829708, 2016). "Protective mechanism of IL-22 in cerulein-induced pancreatitis involves the inhibition of autophagosome formation, which correlates with elevated levels of the anti-autophagic proteins Bcl-2 and Bcl-XL observed in the pancreatic tissues of IL-22 transgenic mice." (PMID 38750415, 2024).
bacterial pneumonia (11 papers, 2014 to 2024). Acute infection of the lung parenchyma caused by bacteria (e.g., Streptococcus pneumoniae, Haemophilus influenzae, Chlamydia pneumoniae, Mycoplasma pneumoniae, and Legionella pneumophila). "It has been demonstrated in both viral and bacterial pneumonia that stimulated ILC3s secrete the cytokines IL-17 and IL-22 to promote both microbial clearance as well as tissue repair." (PMID 33968082, 2021). "As ILC3s are maintained in lung tissue and can rapidly produce IL-17 and IL-22 upon stimulation, it is clear that they play an important role in the innate immune response against bacterial pneumonia." (PMID 33968082, 2021). "Taken together, our data highlighted the role of the IL-22/IL-22BP system during bacterial pneumonia and the need for additional studies to assess its therapeutic interest for patients suffering from bacterial pneumonia or ARDS." (PMID 28887540, 2017). "In this respect, both NKT cells and γδ-T cells have been identified as major sources of IL-17 production at mucosal surfaces, providing protection against P. aeruginosa, and NK cells have been shown to secrete IL-22 following Gram-negative pneumonia." (PMID 28680858, 2017). "As with viral infection, IL-22 also plays key roles in host response to bacterial pneumonia." (PMID 30761149, 2019). "IL-22 BP is a soluble inhibitor of the IL-22 receptor that could be a major regulator of IL-22 in the context of bacterial pneumonia." (PMID 28887540, 2017). "Our data demonstrate that these effects are an indirect consequence of IL-22-mediated expansion of IS-derived BC followed by their re-differentiation to yield IS hyperplasia and provide insights into mechanisms of protection against secondary bacterial pneumonia after respiratory viral infection." (PMID 37726288, 2023). "Both IL-22 and IL-17 (IL-17R signaling) have been demonstrated to play crucial roles in maintaining the local control of Gram-negative pulmonary pathogens and regulate the secretion of CXC chemokines, which are involved in the recruitment of neutrophils against bacterial pneumonia." (PMID 28899359, 2017).
endotoxemia (11 papers, 2013 to 2025). "Another study has shown that IL-22 is pathogenic in a murine model of systemic endotoxemia." (PMID 34597299, 2021). "Since NFAT in T-cells can be engaged by T-cell receptor-independent mechanisms connecting to innate immunity, enhanced NFAT-c2 may also contribute to the current observation of hypothermia-associated IL-22 upregulation during murine endotoxemia." (PMID 28706520, 2017). "Studies reveal that ethanol decreases Akkermansia in mice, but IL‐22 treatment can elevate this symbiont, restoring alcohol‐reduced Reg3γ and α‐defensin levels, restoring intestinal barrier function, and reducing endotoxemia." (PMID 41362700, 2025). "To explore the role of IL-22 in the LPS-induced endotoxemia mice model, we treated mice with LPS or LPS plus F-652." (PMID 36123595, 2022). "IL-22 is reduced in the intestine of obese mice, and restoration of IL-22 decreases metabolic abnormality by targeting intestinal permeability and endotoxemia." (PMID 35958560, 2022). "Our study suggests that IL-22 has a protective role against endotoxemia by inducing the development of immunosuppressive cells through S100A9." (PMID 36123595, 2022). "IL-22 (F-652) protects against LPS-induced cytokines storm in the LPS-induced endotoxemia model by inducing the expression of APPs from the liver, like S100A9, and thereby inducing F4/80+Ly6GhiLy6Chi M2-like suppressor cells differentiation." (PMID 36123595, 2022). "Specifically, indigo increased Lactobacillus bacteria and elicited IL-22 production in the gut, which improved intestinal barrier permeability and reduced endotoxemia." (PMID 30944419, 2019). "IL-22 also improved gut barrier integrity and decreased endotoxemia in alcohol-fed mice." (PMID 37908362, 2023). "In summary, our findings suggest that F-652 (IL-22) protects mice against LPS-induced endotoxemia by promoting M2-like macrophage polarization, and this process may depend on S100A9." (PMID 36123595, 2022). "Therefore, IL-22 induced more suppressive Ly6Chi cells in the LPS-induced endotoxemia model, probably by inducing S100A9 production in the liver." (PMID 36123595, 2022). "Hence, to investigate the possible function of IL-22 in endotoxemia, F-652 was injected into LPS-induced endotoxemia mice." (PMID 36123595, 2022). "Interleukin 22 (IL-22) has been shown to play critical roles in the modulation of infectious diseases, but its function in regulating immune responses during endotoxemia remains unclear." (PMID 36123595, 2022). "IL-22 has been previously shown to be reduced in the intestine of obese mice and restoration of IL-22 decreases metabolic abnormality by targeting intestinal permeability and endotoxemia." (PMID 30944419, 2019). "Since IL-22 could promote the polarization of the M2-like macrophages, we hypothesized that F-652 might promote the polarization of the M2-like macrophages and thus suppress the inflammatory response in the LPS-induced endotoxemia model." (PMID 36123595, 2022). "Therefore, it remains unclear whether IL-22 plays an important role in endotoxemia and whether it can regulate the polarization of M2 macrophages in the LPS-induced endotoxemia model." (PMID 36123595, 2022). "However, the potential role and underlying mechanisms of IL-22 in endotoxemia are not clear yet." (PMID 36123595, 2022). "Lipopolysaccharide (LPS) was used to induce endotoxemia mouse model with or without a recombinant fusion protein containing human IL-22 (F-652)." (PMID 36123595, 2022). "Notably, as compared to RT, an ambient temperature of 4°C without endotoxemia failed to significantly affect splenic and colonic il22 expression." (PMID 28706520, 2017). "Experimental observations indicate that IL-22 application in murine endotoxemia fails to significantly affect production of the pro-inflammatory cytokines TNFα, IL-6, and IFNγ analyzed in the early phase (up to 8 h after onset of endotoxemia) of the syndrome." (PMID 23382730, 2013).